CDHR5 (cadherin related family member 5)
Description:
Intermicrovillar adhesion molecule that forms, via its extracellular domain, calcium-dependent heterophilic complexes with CDHR2 on adjacent microvilli. Thereby, controls the packing of microvilli at the apical membrane of epithelial cells. Through its cytoplasmic domain, interacts with microvillus cytoplasmic proteins to form the intermicrovillar adhesion complex/IMAC. This complex plays a central role in microvilli and epithelial brush border differentiation.
Synonyms: MLPCDH; MUCDHL; MUPCDH; FLJ20219; MU-PCDH
Tractability: Antibody: UniProt places it where antibodies can reach, with high confidence; its Gene Ontology location is reachable by antibodies, with high confidence; UniProt predicts a signal peptide or a membrane-spanning region.
Gene: Protein-coding gene on chromosome 11 (616,405 to 626,078, reverse strand). Ensembl gene ENSG00000099834.
Subcellular location: Apical cell membrane; Cell projection, microvillus membrane
Gene Ontology:
Molecular function: beta-catenin binding; cell adhesion molecule binding; protein binding; calcium ion binding
Biological process: brush border assembly; intermicrovillar adhesion; regulation of microvillus length; cell adhesion; cell-cell adhesion; homophilic cell-cell adhesion
Cellular component: apical plasma membrane; brush border membrane; extracellular exosome; microvillus; microvillus membrane; plasma membrane; synapse; clathrin-coated pit; membrane
Genetic constraint (gnomAD): Loss-of-function variants: 80 observed, 65.15 expected, observed/expected ratio (o/e) 1.23, 90% interval 1.02 to 1.48. The synonymous counts are far from expectation, so gnomAD's model fits this gene poorly and the ratio says little. Missense variants: 1,257 observed, 1,109.9 expected, observed/expected ratio (o/e) 1.13, 90% interval 1.08 to 1.19. Synonymous variants: 586 observed, 483.27 expected, observed/expected ratio (o/e) 1.21, 90% interval 1.13 to 1.3.
Homologues: Orthologues: macaque CDHR5 (91% identical), chimpanzee CDHR5 (90% identical), rat Cdhr5 (59% identical), mouse Cdhr5 (59% identical), guinea pig CDHR5 (58% identical), pig CDHR5 (55% identical), dog CDHR5 (51% identical), tropical clawed frog CDHR5 (33% identical). Paralogues in human: DCHS2 (19% identical), CDH23 (18% identical), DCHS1 (17% identical), CDH11 (16% identical), CDH2 (16% identical), CDH1 (16% identical), CDH24 (16% identical), CDH9 (16% identical), CDH12 (15% identical), CDH15 (15% identical), CDH18 (15% identical), CDH20 (15% identical), and 21 more.
Diseases named in the same sentence as CDHR5 in open-access papers:
CDHR5 is named in the same sentence as 35 diseases in open-access papers, as found by Europe PMC text mining. Sharing a sentence is not in itself a finding about the gene and the disease. The quoted sentences say what the papers report.
colon cancer (6 papers, 2015 to 2023). "CDHR5 has been investigated as a biomarker for solid tumors such as colon cancer or renal cell carcinoma." (PMID 32651463, 2020). "Further IHC staining showed that CDHR5 expression in colon cancer also showed a decreasing tendency from low‐grade tumours to high‐grade tumours." (PMID 33025744, 2020). "However, it is conceivable that CDHR5‐mediated ß‐catenin regulation is important in pathological conditions such as colon cancer development or mucosal regeneration after injury." (PMID 37691494, 2023). "Reduced expression of Cadherin-Related Family Member 5 (CDHR5) was recently found implied in carcinogenesis of colon cancer, but its role in other tumors is unknown." (PMID 29088846, 2017). "Mucin and cadherin-like protein (MUCDHL), also called cadherin-related family member 5 (CDHR5), belong to the cadherin-related family, which showed the strongest stimulation in expression profiling of all cadherins after 5-ASA treatment of colon cancer cells." (PMID 37446747, 2023).
colorectal cancer (4 papers, 2015 to 2020). A primary or metastatic malignant neoplasm that affects the colon or rectum. "Studies in colorectal cancer have also indicated that the expression level of CDHR5 mRNA in inflammatory or neoplastic intestinal mucosa was significantly lower than that in normal colon mucosa." (PMID 33025744, 2020). "Studies on renal cell carcinoma, colorectal cancers and liver cancers revealed the low expression of CDHR5 on the surface of tumour cells and its correlation with poor prognosis." (PMID 33025744, 2020). "Recent studies showed that CDHR5 downregulation is a common event in colorectal carcinoma cells." (PMID 29088846, 2017). "In contrast, mesalazin therapy leads to a growth arrest due to higher CDHR5 expression in colorectal carcinoma (CRC) by inducing an increased transcription of the cyclin-dependent kinase inhibitor (p21waf-1) gene." (PMID 29088846, 2017).
liver cancer (3 papers, 2020 to 2025). An epithelial or non-epithelial malignant neoplasm that arises from the liver. "Antigenicity, molecular weight, subcellular localization and expression site predictions were used to shortlist liver cancer associated proteins including AMBP, CFB, CDHR5, VTN, APOBR, AFP, SERPINA1 and APOE." (PMID 39752339, 2025). "Furthermore, aquaporin 9 (AQP9), known to inhibit liver cancer growth and metastasis, and cadherin-related family member 5 (CDHR5), which suppresses HCC cell proliferation, were up-regulated in the Matrigel group." (PMID 40852642, 2025).
renal cell carcinoma (3 papers, 2017 to 2020). "CDHR5 expression appears to be a promising and new independent prognostic biomarker in renal cell carcinoma." (PMID 29088846, 2017). "CDHR5 expression was immunohistochemically examined using tissue micro arrays (TMAs) covering 279 patients with primary renal cell carcinoma." (PMID 29088846, 2017). "We aimed to analyze the expression of CDHR5 in different subtypes of renal cell carcinoma." (PMID 29088846, 2017).
clear cell renal cell carcinoma (2 papers, 2017 to 2020). "CDHR5 loss appears to be a promising prognostic biomarker for clear cell renal cell carcinoma patients." (PMID 29088846, 2017).
cyst (2 papers, 2015 to 2017). A sac-like closed membranous structure that may be empty or contain fluid or amorphous material. "In addition to that, CDHR5 promoter methylation is a possible prognostic biomarker for cyst growth in polycystic kidney disease." (PMID 29088846, 2017).
systemic sclerosis (2 papers, 2017 to 2024). A chronic disorder, possibly autoimmune, marked by excessive production of collagen which results in hardening and thickening of body tissues. "In relation to pathogenesis CDHR5 influence is described for gallstone disease and systemic sclerosis." (PMID 29088846, 2017).
adenoma (1 paper, 2015). A neoplasm arising from the epithelium. "This study has compared MUPCDH (CDHR5) expression in three key types of colorectal tissue samples, for normal mucosa, adenoma, and carcinoma." (PMID 25972897, 2015).
cervical cancer (1 paper, 2021). A primary or metastatic malignant neoplasm involving the cervix. "CDHR5 was the first identified hub gene to be negatively correlated with DDR or hypoxia in cervical cancer, which had potential effects on the treatment of immune checkpoint inhibitors (ICIs)." (PMID 35071000, 2021). "However, a significant higher count of B cell, CD8 positive T cells, resting CD4 positive T memory cells, regulatory T cells, gamma delta T cells, and resting NK cells were presented in cervical cancer samples with high CDHR5 expression." (PMID 35071000, 2021). "This is the first study that suggested the negative correlation between CDHR5 and DDR or hypoxia in the cervical cancer, which merited further study." (PMID 35071000, 2021). "Moreover, we found the association between DDR alteration, hypoxia feature, and tumor microenvironment in cervical cancer, namely, the negatively regulated hub gene CDHR5, suggesting that DDR alteration(s) could not function as a robust predictor of ICIs in cervical cancer patients." (PMID 35071000, 2021).
chronic pancreatitis (1 paper, 2020). A chronic inflammatory process causing damage and fibrosis of the pancreatic parenchyma. "The CDHR5 IHC staining was performed in forty‐seven pancreatic tissues with different pathological grades, including 12 (25%) chronic pancreatitis (CP), 16 (34%) PanIN1, 10 (21%) PanIN2, 3 (7%) PanIN3 and 6 (13%) PDAC." (PMID 33025744, 2020).
colitis (1 paper, 2023). Inflammation of the colon. "CDHR5∆/∆ and CDHR5+/∆ mice were more sensitive to DSS‐induced colitis as indicated by a pronounced weight loss." (PMID 37691494, 2023). "We investigate the role of microvillus crosslinking in colitis in mice with deletion of the IMAC component CDHR5." (PMID 37691494, 2023). "CDHR5‐deficient mice were not more sensitive to these colitis models, which result in rapid (within 1–2 days) immunological destruction of intestinal epithelial cells." (PMID 37691494, 2023). "We have not observed spontaneous colitis in CDHR5‐deficient mice nor has it been reported in CDHR2‐ and TMIGD1‐deficient mice." (PMID 37691494, 2023). "Our study shows that CDHR5‐dependent microvillus crosslinking in the intestinal brush border prevents DSS‐induced bacterial invasion and colitis." (PMID 37691494, 2023). "Consistently, shortening of the colon length as indicator for colitis severity was increased in DSS‐treated CDHR5∆/∆ and CDHR5+/∆ mice but not oxazolone‐ or TNBS‐treated mice." (PMID 37691494, 2023). "Our data demonstrate that CDHR5 protects against DSS‐induced colitis, which is based on induction of epithelial damage, but not against immune‐based oxazolone‐ or TNBS‐induced colitis." (PMID 37691494, 2023).
Headache (1 paper, 2025). Cephalgia, or pain sensed in various parts of the head, not confined to the area of distribution of any nerve. "Among these associations, 108 proteins were associated with headache, of which C4BPB (odds ratio [OR] = 1.59, P = 1.67 × 10−39), IL18R1 (OR = 1.55, P = 7.36 × 10−25), and CDHR5 (OR = 1.46, P = 6.31 × 10−23) had the strongest associations." (PMID 40048323, 2025).
Hyponatremia (1 paper, 2024). An abnormally decreased sodium concentration in the blood. "Hypermethylation of cg11464053 decreases CDHR5 expression and contributes to renal injury, disrupted fluid-electrolyte balance, and laboratory finding of hyponatremia." (PMID 38594575, 2024).
pancreatic adenosquamous carcinoma (1 paper, 2020). A carcinoma that arises from the pancreas showing both ductal and squamous differentiation. "In our study, we also analysis CDHR5 expression in pancreatic adenosquamous carcinoma in the TMA, outcomes suggested that CDHR5 was down‐regulated in this pancreatic cancer subtype, which was different from that in PDAC (data not shown)." (PMID 33025744, 2020).
pancreatic cancer (1 paper, 2020). "Results showed that CDHR5 was extremely highly expressed in pancreatic tumour tissues and its high expression was associated with tumour metastasis." (PMID 33025744, 2020). "Results also showed that CDHR5 expression was significantly higher in pancreatic tumours compared to that in adjacent normal tissues." (PMID 33025744, 2020). "In addition, cellular and molecular studies have been applied to further explored the roles of CDHR5 in pancreatic cancer cells and the potential mechanisms." (PMID 33025744, 2020). "CDHR5 has been reported to play key roles in carcinogenesis of various cancers, but its roles in pancreatic cancer have not been reported." (PMID 33025744, 2020). "However, the roles of CDHR5 in pancreatic cancer have not been reported." (PMID 33025744, 2020).
rheumatologic disorders (1 paper, 2024). "These authors validated cadherin-related family member 5 as a potential biomarker for autoimmune ILD in patients with rheumatologic disorders." (PMID 39168282, 2024).
ulcerative colitis (1 paper, 2023). An inflammatory bowel disease involving the mucosal surface of the large intestine and rectum. "Single‐cell RNA sequencing data of patients with ulcerative colitis reveals downregulation of CDHR5 in enterocytes of diseased areas." (PMID 37691494, 2023).
tumor (8 papers, 2014 to 2023). "Investigation of the putative functional role of CDHR5 using TCGA data and Enrichment analysis for Gene Ontology and Pathways revealed associations with many metabolic and some tumor growth-associated processes and pathways." (PMID 29088846, 2017). "Tissue microarray‐based immunohistochemistry was performed to analyse the correlation between CDHR5 expression and clinical and pathological features of PDAC, as well as the CDHR5 expression during tumour progression." (PMID 33025744, 2020). "As PDAC patients with tumour metastasis were excluded according to the criteria, the potential relation between CDHR5 and tumour metastasis was obscured inevitably." (PMID 33025744, 2020). "A stratified analysis of CDHR5 expression according to histological tumor subtype showed, that CDHR5 is mostly expressed in clear cell and papillary RCC (77.3% and 78.1% positive cases, respectively) whereas chromophobe RCC (n=9) showed no expression at all." (PMID 29088846, 2017). "A possible mechanism is the ability of CDHR5 to retain β-catenin on the plasmatic membrane in CRC tumor cells." (PMID 29088846, 2017). "In 100 (35.8%) of the 279 RCC tumor samples CDHR5 was expressed solely luminal." (PMID 29088846, 2017). "Moreover, Felix's study also suggested the correlation between CDHR5 expression and pT stage of renal tumours, which could be explained as the outcomes of CDHR5‐M in tumour proliferation." (PMID 33025744, 2020). "This phenomenon might be ascribed to the differentiation of CDHR5 functions in different tumours." (PMID 33025744, 2020). "Previous studies have suggested controversial roles of CDHR5 in the cancer progression in different cancer types, but according to the decreased expression level in tumor tissues than the adjacent non-tumor tissues, it’s more likely to function as tumor suppressor." (PMID 35071000, 2021). "In other words, CDHR5 might not remarkably affect tumour proliferation of PDAC while participate in metastasis process of tumour cells." (PMID 33025744, 2020). "Of interest, we identified the top 10 differentially mutated genes between APOBEC-enriched and non-APOBEC-enriched samples, and among these, KRAS, CDHR5, JAK2, and MAP2K4 were previously shown to be closely related to tumor development." (PMID 32670354, 2020).
cancer (4 papers, 2015 to 2022). A tumor composed of atypical neoplastic, often pleomorphic cells that invade other tissues. "Considering that CDHR5 presents a high expression level in PDAC, this finding demonstrated that CDHR5 might play a role in promoting cancer in PDAC." (PMID 33025744, 2020).
CDHR5 also shares sentences with these, for which no sentence is quoted: Renal cyst (2 papers); Alzheimer disease (1); chordoma (1); chromophobe renal cell carcinoma (1); colorectal tumors (1); deafness (1); depression (1); inflammatory bowel disease (1); membranous nephropathy (1); pancreatic ductal adenocarcinoma (1); papillary renal cell carcinoma (1); polycystic kidney disease (1); pulmonary disease (1); renal carcinoma (1); vascular dementia (1); Wilms tumor (1).